CD14 (CD14 molecule)
Diseases named in the same sentence as CD14 in open-access papers (continued):
Sharing a sentence is not in itself a finding about the gene and the disease.
experimental autoimmune encephalomyelitis (5 papers, 2017 to 2023). An autoimmune demyelinating disease of the central nervous system that is produced experimentally in animals by the injection of homogenized brain or spinal cord in Freund's adjuvant. "Previous studies have also reported that CD14 deficiency increased clinical symptoms in active experimental autoimmune encephalomyelitis." (PMID 27878450, 2017). "·↓ Human CD14+ monocyte-derived dendritic cell differentiation.·↓Duction in the EAE (experimental autoimmune encephalomyelitis) clinical score.·↓ Inflammatory Th1 and Th17 cells in EAE." (PMID 28289385, 2017). "Vorinostat has been shown to inhibit the differentiation, maturation, and endocytosis of human CD14(+) monocyte-derived dendritic cells and further inhibit their stimulation of allogeneic T-cell proliferation, thereby ameliorating experimental autoimmune encephalomyelitis." (PMID 37762402, 2023). "Classical inflammatory CD14++CD16− monocytes, with high CD192 (also known as CCR2, a chemokine receptor that binds monocyte chemoattractant proteins, MCP-1) expression, due to interleukin-1β (IL-1β) secretion cross the blood–CNS barrier before experimental autoimmune encephalomyelitis onset." (PMID 37893243, 2023).
familial hypercholesterolemia (5 papers, 2007 to 2024). An inheritable form of hyperlipidemia, in which there are excess lipids in the blood. "This link with hypercholesterolemia might highlight that rs2569190A>G in CD14 could be implicated in the pathophysiology of hypercholesterolemia." (PMID 31671579, 2019). "Thus, we concluded that rs2569190G in CD14 is associated with a higher risk of developing hypercholesterolemia." (PMID 31671579, 2019). "In addition, high plasma cholesterol contractions in patients with familial hypercholesterolemia were found to be associated with a high proportion of circulating CD14+ and CD16+ monocytes and monocyte-derived microparticles compared with levels documented in a healthy control group." (PMID 27481939, 2016). "This might point to a possible role for CD14 in the pathophysiology of hypercholesterolemia." (PMID 31671579, 2019). "C57BL/6 mice developed hypercholesterolemia on a 4 wk HCD, accompanied by an inflammatory state with increased SAA and CD14." (PMID 17997851, 2007).
gastric tumor (5 papers, 2013 to 2024). "Consistently, overexpression of CD14 and TLRs in H. pylori infected gastric mucosa has been observed, particularly in gastric tumor tissues." (PMID 23338226, 2013). "To shed light on myeloid populations present in gastric tumors, we re-clustered the 10,546 myeloid cells in our dataset and identified fifteen subclusters which were subsequently determined to be either macrophages (CD68, CD14), dendritic cells (FLT3, FCER1A), or neutrophils (CSF3R)." (PMID 36550535, 2022).
Hepatic steatosis (5 papers, 2017 to 2024). Steatosis is a term used to denote lipid accumulation within hepatocytes. "Our mechanistic studies in HFD-induced NAFLD mice potentially implied that PNS supplementation improved hepatic steatosis and fibrosis via inhibition of hepatic CD14 and TLR4 activation." (PMID 33656663, 2021).
hyperlipidemia (5 papers, 2013 to 2024). "In our study, macrophages from ApoE−/− mice showed inhibited transcription of TLR2, TREM-1, TREM-3, and CD14 in quiescent state, whereas only TREM-1 expression was influenced by hyperlipidemia in bacteria stimulated macrophages." (PMID 23977160, 2013). "We did not identify any associations between CD14+CD16+ monocyte transmigration and cognition in those who did or did not smoke or those with or without hyperlipidemia." (PMID 39253970, 2024).
infarction (5 papers, 2013 to 2025). A localised pathological necrosis of tissue resulting from obstruction of the blood supply usually by a thrombus, an embolus, or vascular torsion. "The positive correlation between CD14+ and PIC indicates that increased CD14+ levels are associated with increased risk or severity of post-infarction cardiosclerosis." (PMID 40218200, 2025). "This correlation suggests that as CD14+ levels increase, the likelihood of more severe post-infarction cardiosclerosis increases." (PMID 40218200, 2025). "CD14+ shows a moderate positive correlation with post-infarction cardiosclerosis, accounting for 37%." (PMID 40218200, 2025). "Additionally, in vivo studies in mouse models of AMI found an increase in the expression of CX3CL1 during phase 2 of infarction, which suggested the mobilization of Ly-6Clow monocytes (mouse counterparts of human CD14++CD16+/CD14+CD16++ monocytes)." (PMID 32676508, 2020).
lupus nephritis (5 papers, 2016 to 2022). Glomerulonephritis in the context of systemic lupus erythematosus. "The CD14 (C-159T) polymorphism was related to increased susceptibility to SLE and could be a promising biomarker for the diagnosis of lupus nephritis." (PMID 35197962, 2021). "Moreover, a study demonstrated that urinary CD14 mononuclear cells could serve as a biomarker for lupus nephritis (LN)." (PMID 35197962, 2021).
meningioma (5 papers, 2020 to 2024). A generally slow growing tumor attached to the dura mater. "This genotyping method and four-colour flow cytometry has enabled us to assess the variability in the largest immune cell infiltrate population, M2 macrophages (CD45+HLA-DR+CD14+CD163+) in 42 meningioma samples, and to suggest that underlying genetics is relevant." (PMID 32070062, 2020). "Flow cytometry analyses revealed single-cell suspensions of meningiomas containing viable immune cells, predominantly CD14+ macrophages and CD8+ T cells, with smaller proportions of B cells and NK cells." (PMID 39682129, 2024). "Next, we analysed 42 meningioma samples for both M2 macrophages (CD45+HLA-DR+CD14+CD163+) and tumour cells (CD45−HLA−DR−CD14−CD44+) at Passage 0, and related these results to mutational status." (PMID 32070062, 2020). "Here, we report a short protocol for the digestion of meningioma tissue into a single-cell suspension that contains viable immune cells that comprise of predominantly CD14+ macrophages, CD3+ T cells, and to a lesser extent CD56+ natural killer (NK) cells, and CD19+ B cells." (PMID 39682129, 2024). "Since these cells were also CD14 high and CD11c intermediate as seen in the gating strategy, this suggests that the cells are macrophages, consistent with previous literature demonstrating the presence of macrophages in meningiomas." (PMID 39682129, 2024). "In contrast, there was a modest but significant increase in relative expression of myeloid markers (CD14, CD33 and CD74) in NF2 meningiomas, suggesting higher infiltration of NF2 tumors by myeloid cells." (PMID 36937440, 2023).
pancreatic ductal adenocarcinoma (5 papers, 2016 to 2025). An infiltrating adenocarcinoma that arises from the epithelial cells of the pancreas. "CD88-CD1c+CD14+ DC3s are found in pancreatic ductal adenocarcinoma tumors." (PMID 40584260, 2025). "A phase 1b clinical trial showed that following administration of PF-4136309 in patients with pancreatic ductal adenocarcinoma (PDAC), levels of CD14 + CCR2+ inflammatory monocytes reduced in the peripheral blood." (PMID 39076996, 2024).
respiratory failure (5 papers, 2020 to 2025). The significant impairment of gas exchange within the lungs resulting in hypoxia, hypercarbia, or both, to the extent that organ tissue perfusion is severely compromised. "We found significant associations between certain genetic loci and critical outcomes, such as rs4957796 in FER and rs2569190 in CD14 associated with mortality, and rs9508032 in FLT1 with respiratory failure." (PMID 40168842, 2025). "Our systematic review revealed significant associations between the genes CD14, FER, and mortality/survival, as well as FLT1 and respiratory failure among critically ill patients." (PMID 40168842, 2025). "For example, CD14 was associated with mortality/survival and multiple organ failure; HMOX1 was associated with kidney failure and respiratory failure; TNF was associated with mortality/survival and respiratory failure." (PMID 40168842, 2025).
serous ovarian carcinoma (5 papers, 2015 to 2024). "In high-grade serous ovarian cancer, CD14+ monocytes play a key regulatory role in tumor progression, including the modulation of tumor inflammation and angiogenesis." (PMID 38600248, 2024). "CD14+ cells from human serous ovarian carcinoma ascites (TAMs) rapidly adhere to cell culture dishes and assume a macrophage-like morphology." (PMID 25968567, 2015).
thrombosis (5 papers, 2015 to 2025). "CD14 is a surface marker for monocyte-macrophages, which is closely related to cerebral venous sinus function and thrombosis and is more suitable for reflecting the immune environment of cerebral venous sinus thrombosis." (PMID 39605979, 2024). "We collected samples from patients with and without thrombosis and compared plasma levels of lipopolysaccharide (LPS), LPS binding protein (LBP), soluble CD14 (sCD14), and von Willebrand Factor antigen level (vWF)." (PMID 25814984, 2015).
urinary tract infection (5 papers, 2012 to 2022). "In human kidneys, CD14++ macrophages have been identified as a subpopulation primed against bacterial infection and responsive to salt gradients in models of urinary tract infections." (PMID 36066976, 2022). "It seems that activation of the CD14/TLR2 and/or CD14/TLR4 pathway during the acute phase, which reflects the general activation of the immune system due to the underlying infection, may play an important role in the limitation of urinary tract infection." (PMID 27252945, 2016). "Furthermore, the uropathogenic E. coli (UPEC) triggers innate responses during urinary tract infection in a TLR4-dependent and CD14-independent manner both in mice and humans." (PMID 23166489, 2012).
acute monocytic leukemia (4 papers, 2012 to 2024). Acute monoblastic leukemia (AML-M5), is one of the most common subtypes of acute myeloid leukemia (AML) that is either comprised of more than 80% of monoblasts (AML-M5a) or 30-80% monoblasts with (pro)monocytic differentiation (AML-M5b). "As expected, M3 (APL) cases were almost completely dominated by the GMP signature, while M4 (Acute Myelomonocytic Leukemia) and M5 (Acute monoblastic/monocytic leukemia) samples resembled CD14+ monocyte cells and GMP." (PMID 38762545, 2024). "Immunophenotypic analysis of the bone marrow showed expression of CD11b, CD13, CD14, CD15, CD33, CD34, CD45 and human leukocyte antigen-DR, findings compatible with the diagnosis of acute monoblastic leukemia (French-American-British classification M5a)." (PMID 22339850, 2012). "Therefore, we confirmed the pharmacological effect of MCL in human acute monocytic leukemia cell line THP-1 and human primary CD14+ monocytes derived from healthy donors." (PMID 26984741, 2016).
alcoholic liver diseases (4 papers, 2014 to 2025). A disorder caused by damage to the liver parenchyma due to alcohol consumption. "Frequency distribution for CD14 gene SNP (rs2569190) genotype/minor allele and its genetic association for Alcoholic liver disease." (PMID 36238273, 2022). "The rs2569190 SNP has shown genetic association with alcoholic liver disease, and the polymorphisms may exert their effects by modulating CD14 expression." (PMID 36238273, 2022). "Overall, in this study, it has been observed that the risk and severity of alcoholic liver disease (ALD) is prevalently more intense among the ALD group, in particular among those individuals having the TT genotype of rs2569190 of the CD14 gene." (PMID 36238273, 2022). "We have also delineated whether the variants of -159C/T (rs2569190) of the CD14 gene are associated with elevated levels of biochemical indices of alcoholic liver damage or not." (PMID 36238273, 2022).
atopic asthma (4 papers, 2011 to 2018). An asthma that is characterized by symptoms that are triggered by an allergic reaction caused by inhaled allergens such as dust mite allergen, pet dander, pollen and mold. "The codominant model for the -260T allele implied a dose-response relationship in CD14 expression and reduction of atopic asthma risk." (PMID 21745379, 2011). "A protective dose-response relationship between the CD14 -260T allele and atopic asthma susceptibility was observed." (PMID 21745379, 2011). "Similarly in a study of children in India the CD14 C-159 T CC genotype was strongly associated with atopic asthma and serum IgE." (PMID 24524443, 2014).
bacterial pneumonia (4 papers, 2010 to 2023). Acute infection of the lung parenchyma caused by bacteria (e.g., Streptococcus pneumoniae, Haemophilus influenzae, Chlamydia pneumoniae, Mycoplasma pneumoniae, and Legionella pneumophila). "In this limited number of patients, soluble CD14 serum levels tended towards a higher sensitivity, specificity and diagnostic accuracy compared to CRP and WBC in the diagnosis of bacterial pneumonia." (PMID 20302606, 2010). "Soluble CD14 levels may serve as a novel biomarker marker for bacterial pneumonia in children." (PMID 20302606, 2010).
celiac disease (4 papers, 2012 to 2020). An autoimmune genetic disorder with an unknown pattern of inheritance that primarily affects the digestive tract. "Of antigen-presenting cells (APCs) expressing HLA-DQ molecules in the celiac disease (CD) lesion, CD11c+ dendritic cells (DCs) co-expressing the monocyte marker CD14 are increased, whereas other DC subsets (CD1c+ or CD103+) and CD163+CD11c− macrophages are all decreased." (PMID 22438948, 2012).
childhood asthma (4 papers, 2006 to 2019). "The aim of this systematic review was to obtain a better insight into the relation between CD14 and toll-like receptors and childhood asthma in Caucasians." (PMID 23496969, 2013). "It has been suggested that factors found in breast milk, such as soluble CD14, a receptor for bacterial lipopolysaccharide (LPS), is important in the prevention of childhood asthma and atopy." (PMID 17185285, 2006). "Consequently, a better insight into the relation between CD14 and TLRs and pathology of childhood asthma in Caucasians would be achieved." (PMID 23496969, 2013).
cholangiocarcinoma (4 papers, 2020 to 2024). A carcinoma that arises from the intrahepatic biliary tree (intrahepatic cholangiocarcinoma) or from the junction, or adjacent to the junction, of the right and left hepatic ducts (hilar cholangiocarcinoma). "We selected 5 markers: CD44 and GPC4 were enriched in EVs from PDAC and cholangiocarcinoma organoids, while VGLUT2, CD14, and annexin A11 were enriched in EVs from PDAC organoids but not cholangiocarcinoma organoids." (PMID 32990680, 2020).
chronic hepatitis C (4 papers, 2014 to 2020). "CD14+ monocytes were purified from 16 chronic hepatitis C patients, including eight genotype 1 patients, seven genotype 2a patients, and one genotype 3 patients." (PMID 31447817, 2019). "CD14+ monocytes were purified from 10 chronic hepatitis C patients, including six genotype 1 patients and four genotype 2a patients." (PMID 31447817, 2019). "Inhibition of MafB in CD14+ monocytes purified from chronic hepatitis C patients induced elevated IFN-α1 secretion, which was accompanied by IRF3 phosphorylation." (PMID 31447817, 2019). "It was found that low proportion of baseline TLR3 expressing CD14+ monocytes was a single predictor of cEVR in chronic hepatitis C patients with antiviral treatment [odds ratio (OR) = 2.11, 95% confidence intervals (CI) (1.15–3.88), P = 0.023]." (PMID 24709775, 2014). "In present study, we found that the level of TLR3 expressing CD14+ monocytes was elevated in chronic hepatitis C patients and further increased at 12 weeks, but returned to baseline level at 24 weeks after treatment with IFNα-2b/RBV or PegIFNα-2a/RBV." (PMID 24709775, 2014). "The current data revealed that overexpression of MafB in chronic hepatitis C patients might suppress type I IFN production by CD14+ monocytes, leading to the viral persistence." (PMID 31447817, 2019). "To seek the role of cellular immune response in chronic hepatitis C patients with antiviral treatment, we investigated the dynamic changes of peripheral Tregs, PD-1 expressing T-cells and TLR3 expressing CD14+ monocytes in the patients." (PMID 24709775, 2014). "However, MafB inhibition did not affect CD14+ monocytes-induced CD4+ T cells differentiation in vitro in chronic hepatitis C patients." (PMID 31447817, 2019). "Importantly, MafB inhibition directly promoted IFN-α1 production, but not IFN-β, by CD14+ monocytes from chronic hepatitis C patients, which was accompanied by IRF3 phosphorylation." (PMID 31447817, 2019).
colorectal tumours (4 papers, 2015 to 2025). "In Visium spatial transcriptomics of human colorectal tumours, there were hotspots enriched in monocyte/macrophage genes (including CD14+CD68+), and expression of CXCL9 and CXCL10 were localised to these regions." (PMID 40523200, 2025). "Sorted CD14+ cells from colorectal tumours and from the peripheral blood strongly suppressed T cell proliferation (p < 0.0001)." (PMID 34727230, 2022).
diabetic nephropathy (4 papers, 2017 to 2021). "Hub genes (FPR3, C3AR1, CD14, ITGB2, RAC2 and ITGAM) related to iron death in diabetic nephropathy were obtained through gene expression differential analysis between different subtypes." (PMID 34735495, 2021). "Finally six Hub genes related to iron death in diabetic nephropathy were obtained, including FPR3, C3AR1, CD14, ITGB2, RAC2 and ITGAM." (PMID 34735495, 2021). "Three subjects with overt diabetic nephropathy had reported history of CVD and corresponding higher levels of CD45_bright/CD14+/OCN+ cells compared to subjects without nephropathy (27.3 ± 3.1% vs 15.1 ± 7.6%, p = 0.03)." (PMID 28915881, 2017).
E. coli infection (4 papers, 2009 to 2022). "Live E. coli infection also upregulates expression of additional constituents of the innate responses, including CD14, TLR2 and PYCARD, proteins that recognize and orchestrate responses to bacterial infection." (PMID 26933871, 2016). "As can be seen, CD14 gene plays a role in immune and inflammatory regulation of porcine with E. coli infection." (PMID 27098998, 2016). "The expression of TLR4, CD14 and MD-2 (encoding MD-2 protein; alternatively known as LY96 encoding Lymphocyte antigen 96 protein) was examined next because E. coli infection is particularly important after parturition and paves the way for other pathogens to cause uterine disease." (PMID 19476661, 2009).
endometrial cancer (4 papers, 2009 to 2025). Primary or metastatic malignant neoplasm involving the endometrium (mucous membrane that lines the endometrial cavity). "However, CD62L on CD62L+ plasmacytoid Dendritic Cell (OR=0.831, 95%CI; 0.699-0.989, P=0.037) and CD14- CD16+ monocyte %monocyte (OR=0.465, 95%CI; 0.227-0.953, P=0.036) were negatively associated with the risk of endometrial cancer." (PMID 38746677, 2024). "Specific subpopulations of extracellular vesicles were enumerated in serum and higher levels of tissue factor-positive, CD14-positive (monocyte-derived) and CD144-positive (endothelial-derived) large extracellular vesicles were identified in endometrial cancer cases." (PMID 40987065, 2025).
enthesitis (4 papers, 2019 to 2025). Inflammation at the site of insertion of ligaments, tendons, and other fibrous structures into bone. "Of note, blocking CD14 significantly alleviated PsA-like skin and joint inflammation, including reduced epidermal hyperplasia, inflammatory infiltration, enthesitis, cartilage damage, and bone erosions." (PMID 40471688, 2025). "We next examined whether the levels of pSTAT3 in Th1 or Tfh cells CD4+ T cells or in CD14+CD16- monocytes were correlated with tender joints (TJ), swollen joints (SJ), enthesitis or C reactive protein (CRP)." (PMID 35087513, 2021).